ERBB2 (erb-b2 receptor tyrosine kinase 2)
Diseases named in the same sentence as ERBB2 in open-access papers (continued):
Sharing a sentence is not in itself a finding about the gene and the disease.
tumor (continued). "Besides ERBB2, the RET receptor tyrosine kinase plays a similar role among the cell surface cohort of tumor-agnostic biomarkers." (PMID 38920700, 2024). "This regulation of glucose and lipid transporters contributes to the enhanced sensitivity of tumor cells to the ketogenic diet and anti-ErbB2 mAb therapy in the absence of Cpt1a." (PMID 39097623, 2024). "Nonetheless, the MCKD was not able to rescue tumor growth in vivo to the level of Cpt1a-proficient ErbB2+ tumor cells." (PMID 39097623, 2024). "A modest anti-tumor effect was further described upon dual inhibition with trastuzumab and afatinib, even for ERBB2-amplified tumors lacking an EGFR amplification." (PMID 38611014, 2024). "Metastatic ErbB2 (HER2) tumour burden was reduced by 75% in BCL3-null mice and this was recapitulated in allografts of BCL3-null tumour cells into wild-type recipient mice, confirming the tumour cell autonomous effects of BCL3 on the metastatic process." (PMID 38195591, 2024). "In this work, we used the commercial design of the 176 gene panel for the tumor analysis based on their relevance and role in oncology from the TCGA project, however, does not include the ERBB2 gene, therefore this amplification was not analyzed in the tumors." (PMID 39264897, 2024). "Although HER2 expression is indicated by amplified or unamplified status, the level of mRNA translating ERBB2 varies proportionately from IHC-0 to IHC-3 for HER2-expressing tumor cells." (PMID 39063972, 2024). "Progression-free survival for trastuzumab therapy in patients with ERBB2 AMP was significantly longer than that in patients with no ERBB2 AMP detected by the targeted tumour sequencing test (median 14 months vs. 4 months, P = 0.007)." (PMID 38862927, 2024). "We achieved significant reduction of the primary tumor volume with desARE3'UTRERBB2-30, achieving 50% complete tumor lysis and inhibiting 60%–80% of liver metastasis, hepatomegaly, and 90% of lung metastasis, through ERBB2 downregulation." (PMID 38699639, 2024). "The violin plot showed the cell-cell interactions while giving the different ligands and receptors in the EGF signaling pathway, and the results showed that C1 SRSF7+ MCs subtype and tumor-cells were mainly contacted with AREG as a ligand and EGFR or ERBB2 as receptors." (PMID 39430754, 2024). "In each case where ERBB2 amplification was not originally detected, the sample with the amplification detected had a higher maxVAF, indicative of increased tumor shed." (PMID 38406801, 2024). "Also, we tested the expression of EGFR, ErbB2, p-AKT, and p-mTOR in 4 groups of tumor tissues through western blot." (PMID 39075515, 2024). "Thus, concern remains for higher on-target off-tumor toxicity with greater CAR-T cell expansion, as seen in a patient treated with ERBB2-CAR-T therapy who experienced fatal cytokine release syndrome from on-target, off-tumor effect." (PMID 39722028, 2024). "We observed several basal-like marker genes expressed in the tumor sample and the lack of ERBB2 amplification and hormonal receptors." (PMID 39239354, 2024). "Two residual tumors failed both IHC and ERBB2 FISH, 1 failed IHC, and 1 residual tumor’s paired pretreatment biopsy failed IHC and FISH, which resulted in 49 and 50 pairs of pretreatment and posttreatment samples for IHC and FISH comparative analyses, respectively." (PMID 38300710, 2024). "The desARE3'UTRERBB2-30 achieved 40% complete tumor lysis, a 20% partial tumor lysis, and 60% ERBB2 negative staining by IHC." (PMID 38699639, 2024). "The desARE3'UTRERBB2-1 and 3 achieved variable complete (20% desARE3'UTRERBB2-3) and partial (60% and 20%) tumor lysis respectively, with 20% ERBB2-negative IHC staining." (PMID 38699639, 2024).
tumor (continued). "Furthermore, distinct copy number alterations such as EGFR or ERBB2 gene amplification could be ascertained by inspecting copy number profiles in conjunction with morphology, revealing both a high likelihood for a particular tumour type and potentially providing additional predictive information." (PMID 38576030, 2024). "Therefore, even though in BALB–neuT mice, αER expression appears to be lost at an early stage of ErbB2/neu-driven carcinogenesis, BPA can nonetheless promote tumor progression by acting via GPR30." (PMID 38892447, 2024). "BC is a diverse tumour; based on the hormone receptors (ER and PR) and HER2 (ERBB2) signatures, BC is clinically classified into three main subtypes: TNBC, tubular ER+ and PR+, and HER2+." (PMID 38528461, 2024). "Thus, we theorize upregulation of CD44 helps pathogens to infiltrate host cells and promote tumor formation by utilizing ERBB1 and ERBB2." (PMID 39981299, 2024). "According to their findings, upregulated ErbB2 in pancreatic acinar cells induces inflammatory changes rather than a tumor, indicating a potential role for ErbB2 in the pancreatic chronic inflammatory processes." (PMID 38533139, 2024). "Based on these findings, BPA intake accelerated ErbB2/neu mammary cancerogenesis in the BALB–neuT mouse model, resulting in an increased number of tumors per mouse, an increased tumor weight, and a concurrent decrease in tumor-free and overall survival." (PMID 38892447, 2024). "Given the ctDNA findings, Human Epidermal Growth Factor Receptor (HER2) expression by immunohistochemistry (IHC) and ERBB2 amplification by next-generation sequencing on the FFPE biopsy material utilizing a somatic tumor panel (Trusight Oncology 500) were also performed." (PMID 40028484, 2023). "Recently, the multifaceted function of tumor cell-derived exosomes has emerged as an important field in cancer research, and in this regard novel, non-canonical mechanisms of action have been reported for both the EGFR and ErbB2." (PMID 36817764, 2023). "The ERBB2 gene amplification uncovered after short-term NET in this tumor is assumed to represent tumor heterogeneity with pre-existing HER2 gene amplification that was likely not captured in the smaller biopsy sample." (PMID 37066270, 2023). "Altogether, NK-92/5.28.z cells, but not parental NK-92 cells effectively killed ErbB2-positive, 3D aRMS tumor spheroids in vitro." (PMID 37662907, 2023). "As NGS tumor profiling becomes more widely available, RNA expression of ERBB2 could be a potential surrogate for HER2 status." (PMID 38136267, 2023). "The heterogeneity of HER2 was defined as the detection of a HER2-negative area by FISH in 10% of the cases or ERBB2 amplification in more than 5% but less than 50% of tumor cells." (PMID 37298631, 2023). "The PNET tumor tissue revealed no somatic mutations, but the RCC tissue harbored somatic mutations in ERBB2, VHL, and PTEN." (PMID 37007151, 2023). "Furthermore, ERBB2 (HR, 2.338; p = 0.002) and NRG4 (HR, 431.763; p = 0.001) were independent prognostic factors for tumor recurrence." (PMID 37174100, 2023). "How to induce HER2 expression in tumor cells without ERBB2 amplification will be a potential strategy for novel anti-HER2 treatments." (PMID 37264417, 2023). "We analyzed tumor samples submitted to Caris Life Sciences (n=64,354), as well as the TCGA (n=10,967), MSK IMPACT (n=10,945) and AACR GENIE (n=96,324) databases for evidence of EGFR, ERBB2 and ERBB4 gene fusions." (PMID 37168365, 2023). "In a recent whole-exome sequencing (WES) study, alterations in numerous genes including AKT1 and ERBB2, RAS pathway activating alterations, AURKA and CCNE2 amplification, and FGFR2 alterations were identified in tumor biopsies from patients with intrinsic or acquired CDK4/6i resistance." (PMID 37475004, 2023). "Oncogenes on these chromosomes gain extra copy number may promote tumor proliferation, such as EGFR on chromosome 7 and ERBB2 on chromosome 17." (PMID 37784106, 2023).
tumor (continued). "In addition to upregulation of HER2 protein in 17 cases, one additional tumor with equivocal HER2 IHC score of 2 + both pre- and post-NET showed ERBB2 gene amplification post-NET." (PMID 37066270, 2023). "While the expression levels of GRB7, MIEN1, ERBB2 and FBXL20 were considerably greater in tumour tissues than in normal tissues (p < 0.001 or p < 0.01), the expression levels of MED1 and CDK12 were significantly lower in tumour tissues than in normal tissues (p < 0.001)." (PMID 37525498, 2023). "Despite low and heterogeneous ErbB2 expression levels, we confirmed sufficient and ErbB2-specific antitumor capacity of NK-92/5.28.z cells against both, r/r 2D patient-derived tumor organoid RMS cells and 3D RMS tumor spheroid models." (PMID 37662907, 2023). "(Erb-B2 Receptor Tyrosine Kinase 2) (ERBB2 or HER2), for example, is expressed more than 100 times in tumor tissues in comparison to non-cancer tissue." (PMID 36631624, 2023). "Indeed, until recently, anti-HER2 treatments were exclusively reserved for patients with the ERBB2 amplification (defined by HER2 IHC 3+ or 2+ with ISH positivity) and no clinical benefits were highlighted for patients with HER2-low tumours." (PMID 37120672, 2023). "Among molecular subtypes, majority (64%) of Luminal-A type tumours were in non-responding group, and none of the ERBB2+ type tumours were in non-responding group." (PMID 38114526, 2023). "While 5 genes were downregulated in tumor tissues, including PLAT, ERBB2, CEACAM1, NOX4, and UCHL1." (PMID 37056778, 2023). "Named based on the expression of previously established marker genes ERBB2 (T062), NTRK1 (T063), MYCN (T064) and TERT (T065), these subtypes may be rooted in the tumor’s lineage." (PMID 36932241, 2023). "Overall, the median (IQR) tumor size was 1.1 (0.8-1.5) cm, and 1234 patients (87.8%) had estrogen receptor–positive ERBB2 (formerly HER2 or HER2/neu), nonoverexpressing BC." (PMID 37733364, 2023). "A phase II neoadjuvant trial of T-DM1 and pertuzumab conducted at the Dana-Farber Cancer Institute first defined HER2 heterogeneity as an area with ERBB2 amplification in >5% but <50% of tumor cells, or a HER2-negative area by FISH." (PMID 36010967, 2022). "However, KSTAR predicts that the tumor has significant levels of both EGFR and ERBB2 activity, similar to WHIM35 and WHIM8, which also respond to lapatinib treatment." (PMID 35879309, 2022). "We found inhibition of DDR1/BCR signaling with EGFR/ERBB2 to be effective independent of KRAS mutation type and status in COAD and additional primary tumor model of GBM." (PMID 35664781, 2022). "Notably, low oral doses of BPA significantly decreased tumor latency and increased tumor multiplicity, tumor volume, and the incidence of metastasis in mammary tumor virus (MMTV)-ErbB2/neu transgenic mice." (PMID 35740686, 2022). "The HER2 status assessment was originally standardised by The American Society of Clinical Oncology and the College of American Pathologists (ASCO/CAP) that published guidelines recommending to test HER2 protein overexpression by IHC and ERBB2 gene amplification by ISH using FFPE tumour tissue." (PMID 35158855, 2022). "The ERBB2 gene is a proto-oncogene whose protein product HER2 is a membrane-bound tyrosine kinase receptor that generates proliferative and anti-apoptotic signals when activated and is an important driver in tumor development and progression." (PMID 35323320, 2022). "Tumor resistance to FGFRis is identified in multiple tumor types and are mostly related to activation of different signaling pathways including MET, Eph3B, ERBB2/3 or EGFR and/or activation of intracellular signaling pathways without tyrosine kinase receptor dependence." (PMID 35444941, 2022).
tumor (continued). "Interestingly, the ERBB2 enrichment of COAD, KICH, KIRC, THYM, and READ tumor groups has a favorable prognosis based on the survival graphs and disease-free survival analysis." (PMID 36172165, 2022). "The predicted receptors in tumor cells included IL6ST and ERBB2." (PMID 35784460, 2022). "A high ERBB2 level also shows a positive relationship with tumor grade and recurrence of PAAD and UCEC, while the deficiency of the ERBB2 gene shows a negative association with tumor grade and recurrence of KICH and KIRC." (PMID 36172165, 2022). "Interestingly, the ERBB2 gene of the UCEC presented DNA promoter demethylation, which is a crucial mechanism to trigger the activation of specific genes within tumor progression." (PMID 36172165, 2022). "Importantly, Retro-2 eviction of both ErbB-2 isoforms from the nucleus resulted in a striking growth abrogation in multiple TNBC preclinical models, including tumor explants and xenografts." (PMID 35534460, 2022). "BC is further classified into several subclasses, characterized by immunohistochemical staining {(e.g., ER, PR, HER2 (ERBB2)}, proliferation marker protein Ki-67 (MKI67), genomic markers (e.g., BRCA1, BRCA2, and PIK3CA), and immunomarkers (e.g., tumor-infiltrating lymphocytes and PD-L1)." (PMID 36232989, 2022). "We identified normal ERBB2 ploidy but significant SNP allelic imbalance in ERBB2 in one patient, which may be due to copy-neutral LOH in tumor." (PMID 35379811, 2022). "Herceptest scoring for ErbB2/Her2 expression revealed no positivity as the characteristic ErbB2 membrane staining was mainly detected in stromal (data not shown) but not in tumor cells." (PMID 36396684, 2022). "EGF pathways play a pivotal role in regulating AR signalling, e.g., ERBB1 (EGFR) expression is enhanced as a function of tumour severity, whilst the expression of ERBB2 (HER2) increases during and following androgen ablation, thus ensuring sustained survival of PCa cells." (PMID 35326402, 2022). "Profiling of phosphorylated ERBB2 and ERBB3 in end-stage tumors indicated that on-target activity of AF was sustained despite tumor progression, pointing to the emergence of alternative resistance mechanisms that could in the future be explored further." (PMID 36355420, 2022). "Nevertheless, ER−PR+ tumors have been traditionally considered for hormonal therapies and even included in the Luminal A group in the absence of ERBB2 amplification in surrogate tumor subtype classifications." (PMID 36358871, 2022). "These aberrant activations of ERBB2, independent of ligand-receptor stimulation, promote tumorigenesis, tumor growth, and progression." (PMID 35911441, 2022). "Moreover, it is known a direct action of NRF2 on proteins involved in chemoresistance such as AKR1C1-3, ABCF2, SLC40A1, as well as on the modulation of important growth factor receptors, such as c-MET, ErbB2 and EGFR regulating tumour growth." (PMID 35453348, 2022). "In addition, we analyzed RNA-seq expression of ErbB2 and DEPTOR in ErbB2-positive BRCA tumor tissues from TCGA." (PMID 33854045, 2021). "In this study, we made a novel observation that DEPTOR translocates to the cell membrane in ErbB2-positive breast tumor tissues, but not in tumor-adjacent normal tissues, and its PDZ domain is responsible for ErbB2 binding." (PMID 33995662, 2021). "Interestingly, tumor cells of more than 50% of HCC cases showed an ErbB2 expression and expression levels were in case of ErbB2 positivity particularly strong (score 3) (in suppl." (PMID 32591879, 2021). "In addition, we found repressed ERBB2 (HER2) and FOXM1 signaling by IPA, both of which are involved in tumor progression and metastasis." (PMID 33743824, 2021). "In the present study, high ERBB2 expression correlated significantly with an elevated KRT20 expression indicative of luminal tumours and with a lower KRT5 expression as a marker for basal tumours." (PMID 34073233, 2021).
tumor (continued). "Breast cancer is pathologically demarcated by a plethora of abnormal gene profiles and transcripts that drive tumor initiation (MYC, Erb-B2 Receptor tyrosine kinase 2 (ERBB2), tumor progression (FOS, JUNB), proliferation and metastasis (epidermal growth factor receptor (EGRF))." (PMID 34299315, 2021). "For instance, a subset of luminal B tumours that also presents ERBB2 amplification was shown to display enhanced glutamine catabolism due to higher MYC activity compared to luminal B tumours without ERBB2 amplification." (PMID 34572926, 2021). "MET mRNA showed a 3-fold increase in the tumor vs non-tumor normal tissue (3.02±2.16), while the expression of ERBB2 seems no change (0.93±0.69)." (PMID 34335943, 2021). "Interestingly, these immunosuppressive protein markers were also significantly (* p < 0.05) correlated with an increased expression of certain tumor markers, such as CD44, B2M, HER2/ErbB2, S6, B7-H3, ER alpha and S100B." (PMID 34944780, 2021). "ERBB2 and GABRAPL were also significantly correlated with tumor grade." (PMID 34759953, 2021). "The main aim of our work was to create a full-length bispecific antibody (BsAb) as a vehicle for the targeted delivery of interferon-beta (IFN-β) to ErbB2+ tumor cells in the form of non-covalent complex of BsAb and IFN-β." (PMID 34944558, 2021). "The second tumor, PS13-1760, was classified as a grade 3 node negative ER+ PR− ERBB2+ (3+) (pT2, pN0) and had a somatic BRCA2 mutation." (PMID 34011996, 2021). "Two variants were found exclusively in cell 2 and not in its tumor (MMP1 and STAT3), whereas two variants were found only in the tumor from which cell 6 was derived (ERBB2 and MLH3)." (PMID 33917394, 2021). "When comparing tumours either by the parity status of the animals or the tumour histotype, there was broad agreement in the findings from the ddPCR with the CNV-by-exome analysis and the original genomic qPCR analysis of the NeuNT/Erbb2 locus." (PMID 34003256, 2021). "Other studies highlighted that ErbB2-CAR.NK92 prolonged survival and induced reduction of primary tumors and metastasis in breast cancer and GBM xenografts, while parallel-unmodified NK92 cells were unable to inhibit tumor progression." (PMID 33806296, 2021). "The level of mRNA expression of ERBB2 and ESR1 was evaluated in 799 tumor samples." (PMID 34198891, 2021). "Moreover, it was reported that MRK-003 treatment reduced the tumor onset and tumor burden in BALB/c-neuT female mice bearing ERBB2-positive breast cancer cells." (PMID 33673088, 2021). "Moreover, other pathways, such as ERBB2 and SHH signaling, have also been shown to be related to tumor growth and proliferation." (PMID 35155179, 2021). "The correlation between the deep learning–predicted ERBB2 status, which we call H&E-ERBB2 score, and distant disease-free survival (DDFS) was investigated on a fully independent test set, which included whole-slide tumor images from 712 patients with trastuzumab treatment status available." (PMID 33597560, 2021). "The lack of ER, PR, and ErbB2 expression renders the tumor unresponsive to hormonal therapies or ErbB2-targeted therapies." (PMID 34708040, 2021). "ErbB2-mediated tumorigenesis involves activation of receptor tyrosine kinases, induction of cyclin D1/CDK activity, and functional restraint by tumor suppressors." (PMID 33946495, 2021). "In this study, the ErbB2-targeting liposomes directly controlled the PI3K-AKT3-mTOR pathway and may be able to downregulate tumor growth." (PMID 32599712, 2020). "A series of serum biomarkers has emerged in recent years, including CA15.3, CEA, CA 27.29, circulating tumor cells (CTC), and circulating erbB-2 extracellular domain that could help determine resistance to hormonal interventions." (PMID 32052382, 2020). "BLI, autopsy, and PCR analysis showed a short delay, but not an abrogation of tumor growth in WT and ERBB2-CAR CIK cell-treated mice compared to untreated controls." (PMID 33193388, 2020).